TIMM50 (translocase of inner mitochondrial membrane 50)
Description:
Essential component of the TIM23 complex, a complex that mediates the translocation of transit peptide-containing proteins across the mitochondrial inner membrane. Has some phosphatase activity in vitro; however such activity may not be relevant in vivo. [Isoform 2]: May participate in the release of snRNPs and SMN from the Cajal body.
Synonyms: TIM50; TIM50L; MGCA9
Tractability: Antibody: UniProt predicts a signal peptide or a membrane-spanning region. PROTAC: ubiquitination databases record sites on it; its protein half-life has been measured.
Gene: Protein-coding gene on chromosome 19 (39,479,795 to 39,493,785, forward strand). Ensembl gene ENSG00000105197.
Subcellular location: Mitochondrion inner membrane; Nucleus speckle (Isoform 2)
Subcellular location (Human Protein Atlas): Mitochondria; Nucleoplasm
Pathways (Reactome):
Protein localization: Mitochondrial protein import
Gene Ontology:
Molecular function: cysteine-type endopeptidase activator activity; interleukin-2 receptor binding; phosphoprotein phosphatase activity; protein binding; protein serine/threonine phosphatase activity; protein tyrosine phosphatase activity; ribonucleoprotein complex binding
Biological process: mitochondrial membrane organization; protein import into mitochondrial matrix; release of cytochrome c from mitochondria; intracellular protein transport
Cellular component: endoplasmic reticulum; Golgi apparatus; mitochondrial inner membrane; mitochondrion; nuclear speck; nucleoplasm; TIM23 mitochondrial import inner membrane translocase complex
Genetic constraint (gnomAD): Loss-of-function variants: 34 observed, 49.59 expected, observed/expected ratio (o/e) 0.69, 90% interval 0.52 to 0.91. The upper end of that interval is the gene's LOEUF score, 0.91, which puts it in group 3 of 6, group 1 being the genes least tolerant of losing a copy. Missense variants: 458 observed, 487.45 expected, observed/expected ratio (o/e) 0.94, 90% interval 0.87 to 1.01. Synonymous variants: 199 observed, 199.12 expected, observed/expected ratio (o/e) 1, 90% interval 0.89 to 1.12.
Gene-disease validity (ClinGen):
ClinGen rates the evidence that TIMM50 causes each of these diseases.
3-methylglutaconic aciduria type 9 (autosomal recessive): Definitive.
Homologues: Orthologues: chimpanzee TIMM50 (99% identical), macaque TIMM50 (98% identical), rabbit TIMM50 (96% identical), guinea pig TIMM50 (94% identical), dog TIMM50 (94% identical), pig TIMM50 (94% identical), mouse Timm50 (92% identical), rat Timm50 (91% identical), tropical clawed frog timm50 (67% identical), zebrafish timm50 (66% identical), Drosophila melanogaster ttm50 (41% identical), Caenorhabditis elegans scpl-4 (38% identical), and 2 more. Paralogues in human: CTDSPL2 (24% identical), CTDSPL (19% identical), CTDSP1 (18% identical), CTDSP2 (17% identical), CTDNEP1 (14% identical).
Diseases named in the same sentence as TIMM50 in open-access papers:
TIMM50 is named in the same sentence as 26 diseases in open-access papers, as found by Europe PMC text mining. Sharing a sentence is not in itself a finding about the gene and the disease. The quoted sentences say what the papers report.
cardiac hypertrophy (7 papers, 2021 to 2024). "The authors also observed an increase in ROS levels and reduced activity of the respiratory complexes in mitochondria of heart tissues from TIMM50-KO mice, which rendered these animals more susceptible to cardiac hypertrophy." (PMID 34360547, 2021). "A zebrafish model of TIMM50 depletion showed cardiac dilation, while a mouse knockout model of TIMM50 showed cardiac hypertrophy." (PMID 35328774, 2022). "Additionally, TIMM50, the mammalian homologue of Tim50, was shown to be involved in steroidogenesis and plays a preventive role in pathological cardiac hypertrophy and several types of cancer." (PMID 39680434, 2024). "Moreover, antioxidant treatment reduces cardiac hypertrophy in Timm50 KO mice, directly implicating oxidative stress in this pathology." (PMID 38828998, 2024). "Furthermore, the relationship between TIMM50 expression and cardiac hypertrophy warrants further investigation." (PMID 34360547, 2021). "Furthermore, TIMM50-knockout (KO) mice were prone to cardiac hypertrophy induced by aortic band surgery, while heart-specific TIMM50 transgenic mice were protected." (PMID 34360547, 2021).
breast carcinoma (5 papers, 2018 to 2023). "TIMM50 depletion has also proven to induce apoptosis in human breast cancer cell lines, whereas Tim50 loss of function in zebrafish resulted in massive apoptosis in the central nervous system associated with cytochrome c release." (PMID 30190335, 2018). "Interestingly, TIMM50 is an anti-apoptotic gene that has been involved in breast cancer cell proliferation." (PMID 29559981, 2018). "According to previous literature, TIMM50 may function as an oncogenetic protein in breast cancer." (PMID 37580654, 2023). "The previous study demonstrated TIMM50 could promote tumor proliferation and invasion in NSCLC by enhancing the phosphorylation of its downstream ERK/P90RSK signaling pathway; TIMM50 facilitated proliferation, migration and chemoresistance in breast cancer cells." (PMID 37259038, 2023).
developmental delay (3 papers, 2022 to 2024). "All TIMM50 mutant patients studied thus far displayed severe neurological pathologies, which include epilepsy, developmental delay, and loss of movement abilities." (PMID 39680434, 2024). "The onset and nature of the clinical presentation were consistent with other reported pathogenic variants in TIMM50 causing MGCA9, including global developmental delay, optic nerve atrophy, generalized white matter loss and infantile spasms, although 3-MGA was not present." (PMID 38828998, 2024).
Intellectual disability (3 papers, 2022 to 2024). "Human TIMM50 mutations lead to neurological effects, including mitochondrial epileptic encephalopathy, intellectual disability, seizure disorders like infantile spasms, and severe hypotonia accompanied by 3-methylglutaconic aciduria." (PMID 39680434, 2024). "Using WES, we found two novel homozygous variants in FBXO31 and TIMM50 genes in four Iranian consanguineous families diagnosed with autosomal recessive neurodevelopmental disorders with intellectual disability." (PMID 35019165, 2022). "Patients presenting with pathogenic mutations in TIMM50 are rare, but common symptoms include severe intellectual disabilities, epileptic spasms, microcephaly, moderate elevation of plasma lactate levels, variable mitochondrial Complex V deficiency and 3-MGA-uria (MGCA9, MIM #617698)." (PMID 36475414, 2022).
melanoma (2 papers, 2023 to 2025). A malignant, usually aggressive tumor composed of atypical, neoplastic melanocytes. "NRAS Q61L melanomas were most enriched for modules 7 (C19orf10, ARF4, KDELR2), 13 (TIMM50, ZBED3-AS1, SERPINF1), and 15 (RAP1GAP, OCA2, PAICS)." (PMID 39796775, 2025). "In the future, we will investigate the mechanism of AL162457.2’s targeted regulation of TIMM50 and contribute to revealing the lncRNA-mRNA network relationship of AL162457.2 in melanoma." (PMID 37580654, 2023).
non-small cell lung carcinoma (2 papers, 2021 to 2022). A group of at least three distinct histological types of lung cancer, including non-small cell squamous cell carcinoma, adenocarcinoma, and large cell carcinoma. "And TIMM50 could predict poor prognosis and promote tumor progression of non-small cell lung cancer patients by ERK signaling." (PMID 35501914, 2022).
rhabdomyosarcoma (2 papers, 2022 to 2024). A rare aggressive malignant mesenchymal neoplasm arising from skeletal muscle. "In rhabdomyosarcoma, miR-7 is reported to downregulate TIMM50 and SLC25A37 and thus promote mitochondrial dysfunction, resulting in cell necroptosis." (PMID 36349193, 2022). "In rhabdomyosarcoma (RMS), miR-7 exerts an anti-tumor effect by targeting mitochondrial proteins SLC25A37 and TIMM50, ultimately inducing necrosis." (PMID 38383747, 2024).
cardiomyopathy (1 paper, 2022). A disease of the heart muscle or myocardium proper. "Genes important in these processes and that are associated with cardiomyopathy include DNAJC19, MAGMAS, TIMM50, MIPEP, XPNPEP3, HTRA2, CLPB and HSPD1." (PMID 35328774, 2022).
colorectal cancer (1 paper, 2022). A primary or metastatic malignant neoplasm that affects the colon or rectum. "Moreover, in a study involving 129 colorectal cancer (CRC) patients, TIMM50 was discovered as a key regulator and prognostic marker of CRC." (PMID 35938038, 2022).
Encephalopathy (1 paper, 2018). Encephalopathy is a term that means brain disease, damage, or malfunction. "We found novel TIMM50 mutations in an infant patient with rapidly progressive, severe encephalopathy, and we analyzed their pathogenicity in the patient‐derived fibroblasts." (PMID 30190335, 2018). "Whole exome sequencing (WES) identified compound heterozygous pathogenic mutations in TIMM50 in an infant patient with rapidly progressive, severe encephalopathy." (PMID 30190335, 2018).
meningioma (1 paper, 2020). A generally slow growing tumor attached to the dura mater. "Grade-wise comparisons on MGI (benign) vs MGII (atypical) meningiomas revealed prominent involvement of TIMM50, SEC23A, MTAP, RPS23, and ADRM1 based on the concordance analysis of highly ranked features from across 20 Machine Learning randomized iterations obtained via the methods of the Ball group." (PMID 32974197, 2020).
tumor (8 papers, 2015 to 2024). "The downstream ERK/P90RSK signaling pathway of TIMM50 (translocase of the inner mitochondrial membrane 50) can enhance the tumor proliferation and invasion of NSCLC via enhancing phosphorylation." (PMID 38841622, 2024). "We validated in vitro that TIMM50 enhanced EC cell proliferation, migration and lactate levels, and promoted tumor growth in vivo." (PMID 37259038, 2023). "In rhabdomyosarcoma (RMS), miR-7 showed the anti-tumor effect to induce necroptosis by targeting mitochondrial proteins SLC25A37 and TIMM50." (PMID 34381023, 2021). "In miR-7 transfected RMS cells, miR-7 acts via its target mitochondrial proteins solute carrier family 25 member 37 (SLC25A37) and translocase of inner mitochondrial membrane 50 (TIMM50) to promote apoptosis and necroptosis, and also impair tumour invasion and lung metastasis." (PMID 36765536, 2023).
cancer (4 papers, 2021 to 2024). A tumor composed of atypical neoplastic, often pleomorphic cells that invade other tissues. "Taken together, findings from these studies indicate that cancer cells produce more TIMM50 than normal cells, either by increasing the TIMM50 promoter activity or by inhibiting the degradation of the TIMM50 transcript, to increase mitochondrial activity." (PMID 34360547, 2021). "Subsequent studies demonstrated upregulation of TIMM50 levels as a survival strategy for various types of cancer cells." (PMID 34360547, 2021). "Furthermore, TIMM50 maintains mitochondrial permeability barrier and inhibits apoptosis, characteristics that may confer chemoresistance to cancer cells." (PMID 34360547, 2021). "Significantly altered functions, pathways, and gene networks revealed alterations in several key genes and cancer-related pathways that may have importance for NSCLC transformation, including FAM83A, ZNF696, UBE2C, RECK, TIMM50, GEMIN7, and XPO5." (PMID 35309509, 2022). "Moreover, gene interaction networks revealed several key genes and cancer-related pathways that may role for early NSCLC transformation and disease progression, including FAM83A, ZNF696, UBE2C, RECK, TIMM50, GEMIN7, and XPO5." (PMID 35309509, 2022).
mitochondrial disease (1 paper, 2024). "Using quantitative proteomics of patient fibroblasts and a CRISPR-Cas9 mediated TIMM50 HEK293 cell model of disease, we have established the first proteomic map of mitochondrial disease associated with TIMM50 pathogenic variants." (PMID 38828998, 2024). "Here we describe a mitochondrial disease patient who is homozygous for a novel variant in TIMM50 and establish the first proteomic map of mitochondrial disease associated with TIMM50 dysfunction." (PMID 38828998, 2024). "Here, we describe a mitochondrial disease patient homozygous for a novel variant in TIMM50 with clinical symptoms consistent with previously reported cases of MGCA9." (PMID 38828998, 2024). "Proteins involved in OXPHOS and mitochondrial ultrastructure are enriched in the TIM23SORT substrate pool, providing a biochemical mechanism for the specific defects in TIMM50-associated mitochondrial disease patients." (PMID 38828998, 2024).
neurological disorders (1 paper, 2024). "Although TIMM50 mutants are mostly associated with neurological disorders, functional characterization of TIMM50 has yet to be reported in neuronal cells." (PMID 39680434, 2024).
TIMM50 also shares sentences with these, for which no sentence is quoted: hypertrophy (2 papers); infantile spasms (2); 3-methylglutaconic aciduria (1); epilepsy (1); Epileptic spasm (1); genetic disorders (1); infection (1); lactic acidosis (1); lung carcinoma (1); microcephaly (1); neurodevelopmental disorder (1).